CD274 (CD274 molecule)
Diseases named in the same sentence as CD274 in open-access papers (continued):
Sharing a sentence is not in itself a finding about the gene and the disease.
infection (536 papers, 2009 to 2026). The state of being infected such as from the introduction of a foreign agent such as serum, vaccine, antigenic substance or organism. "During infection or inflammation, CD274 encodes an immune inhibitory receptor ligand that hinders T cell activation and cytokine production—an essential reaction for maintaining homeostasis of the immune response." (PMID 38178237, 2024). "Even though CD274 (PD-L1) is associated with regulation of T cell function, this protein is highly upregulated during the acute infection phase and therefore considered an activation marker." (PMID 39263222, 2024). "At day 3 post-infection, young and aged neutrophils expressed similar levels of Il1b, but young neutrophils expressed higher levels of Il1a; the chemokines Ccl3, Cxcl3, and Cxcl1; and Cd274 (encodes PD-L1)." (PMID 37852965, 2023). "Klebsiella-mediated induction of inhibitory molecule CD274 on lung DC may be important in limiting antibacterial effector T cell responses and promoting infection-associated immunosuppression." (PMID 24044871, 2013). "The genes for which the expression was higher in the lungs of WT than those of IFN-γR−/−mice in response to H37Rv infection included Mhc-II, CD274, Cd86, and Cd40, which are all involved in the synapse between antigen-presenting cells and T cells." (PMID 38803236, 2024). "Changes in expression levels of three different transcripts regulated during infection by L. donovani amastigotes (Ccl5), promastigotes (Cd274) or both (Hmox1) was confirmed by RT-qPCR experiments." (PMID 35430587, 2022). "Highly expression of the inflammatory factors from IL-1 family such as IL-1α, IL1-β, and IL-RN was found in C13-PD-L1+ (CD274+) neutrophils at the early stage of infection (day 1 p.i.)." (PMID 32101596, 2020). "In persistent AV [lymphocytic choriomeningitis virus (LCMV)] infections tolerance is the result of suppressive PD-L1 (CD274) signals that engage T cell expressed PD-1 (CD279) receptors, limiting effector T cell clearance and causing T cell anergy." (PMID 25601858, 2014). "During infection, Cd274 was upregulated by the ependyma (Supplementary 1D)." (PMID 41409145, 2025). "We compared the percentage of positivity for these markers on individual infected or non-infected cells on the same microscope slide to determine whether CD274 expression and apoptosis were related to the infection of stromal cells." (PMID 40245043, 2025). "From the results of three independent experiments, we found that the inability to undergo autophagy during infection led to higher expression of many pro-inflammatory genes as compared to autophagy-competent cells, including established ISGs, such as Psmb10, Cd274, Cxcl10, Irf1 and Tap1." (PMID 29748576, 2018). "Stabilization of ATG5DD decreased CD274 expression following infection with either viral strain." (PMID 29748576, 2018). "These included chemokine ligand IP-10 and genes controlled by pro-inflammatory cytokines TNF-α, IL-1β, IFN-γ; namely, interferon regulatory factor 1, Cd274 antigen, metallothionein 2, proteasome subunit (Psmb9), and tumor necrosis factor Tnfsf10 were progressively up-regulated after infection." (PMID 20082697, 2010). "Moreover, Isg12+Cst7+ neutrophils expressed Cd274 and Il10rb, potentially interacted with activated cytotoxic T cells and Slamf9+ macrophages, and jointly established the favoring niches for the resolution of inflammation at the late stage of infection." (PMID 39414783, 2024). "Moreover, the recovery of circulating pDC numbers was accompanied by a decreased expression of CD86 and CD274, suggesting that the antigen presentation or tolerogenic function of pDCs might be limited during the acute phase of the infection." (PMID 34276693, 2021).
infection (continued). "The mRNA expression levels of CD80, CD274, and CD28 in the liver were increased at 6 w after infection, which was consistent with the sequencing results." (PMID 39590301, 2024). "Based on antibody availability, we selected five proteins (FCGR3, FCGR1, CD274, ICAM1, SLAMF8) to profile 24 h after infection with pseudotyped HIV-1 by flow cytometry in CD14- CD11cHi HLADR+ DCs from our cultures." (PMID 29378643, 2018). "Stromal cells infected with either AV or Josiah were more frequently positive for CD274, but the infection had no notable impact on cCasp3 expression." (PMID 40245043, 2025). "However, subsequent infection of N87p-TRAS with HV-HP partially reversed this effect, leading to increased expression of CD274 (p<0.01)." (PMID 40642068, 2025). "With IFNγ blockade, genes in cluster 2, including IL18R1, IDO1, CXCL11, CD274 (PD-L1), and PTPN2, were similarly expressed at day 3 post-infection but were more highly expressed at day 7 compared to controls and had increased expression over the day 3 timepoint." (PMID 38950078, 2024). "Furthermore, surface expression of CD274 and class I major histocompatibility protein H-2Kb were reduced by ATG5DD stabilization 16 h post-infection." (PMID 29748576, 2018). "Along with CD38, CD274 (PD-L1) and CD40 also presented a higher expression in the IND group after infection although no significance was observed." (PMID 35873155, 2022).
adenocarcinoma (416 papers, 2012 to 2026). A common cancer characterized by the presence of malignant glandular cells. "Immune checkpoint blockade (ICB) gene analysis further revealed significant upregulation of LAG3, PDCD1, PDCD1LG2, HAVCR2, and CD274 in the solid pattern adenocarcinomas." (PMID 38505588, 2024). "In clinical analysis of adenocarcinoma patients with stage 1 (middle), patients with high PLK1/VIM/CD274 had shorter OS times than those with low PLK1/VIM/CD274 (n = 346, HR = 2.527, log rank P = 0.0246)." (PMID 33963314, 2021).
immune dysfunction (81 papers, 2011 to 2025). "Notable differences were also observed in immune dysfunction, immune rejection scores, CD274, and CD8 expression between the two risk groups." (PMID 40612108, 2025). "We further analysed the targeted CAF, CD274, and immune dysfunction." (PMID 38911387, 2024). "Therefore, regardless of TIDE, immune dysfunction, CAF, and CD274 scores, patients in the high MMP score group consistently had better survival than those in the low, indicating the value of the MMP score in predicting the therapeutic effect on ICB." (PMID 38911387, 2024).
gastrointestinal tumors (61 papers, 2013 to 2026). "Our study helps to understand the vital roles of CD274/PDCD1LG2 in gastrointestinal tumor-immune interactions." (PMID 33833994, 2021). "In this regard, taking advantage of the large data sets from TCGA, this study aimed to examine the expression profiles of CD274/PDCD1LG2 and the prognostic significance in human gastrointestinal tumors." (PMID 33833994, 2021).
benign tumor (15 papers, 2016 to 2025). "This is also supported by the finding that CD274 is present only on a subset of eosinophils from inflamed hearts and the finding that the proportion of CD274-expressing cells was not different in the spleen of challenged mice, irrespective of heart inflammation (data not shown)." (PMID 41050650, 2025).
inflammation (10 papers, 2021 to 2024). Aberrant reaction of the microcirculation characterized by movement of fluid and leukocytes from the blood into extravascular tissues. "To identify drivers of PD-L1 expression in astrocytes during autoimmune CNS inflammation, we stimulated primary mouse astrocytes with a range of mediators associated to an inflammatory milieu and measured Cd274 expression by RT-qPCR." (PMID 37689786, 2023).
CD274 also shares sentences with these, for which no sentence is quoted: pneumonitis (216 papers); small cell lung carcinoma (199); diffuse large B-cell lymphoma (181); nasopharyngeal carcinoma (133); hematologic malignancies (130); multiple myeloma (106); Merkel cell carcinoma (101); mesothelioma (96); hypophysitis (90); hypothyroidism (90); metastatic carcinoma (80); GEJ adenocarcinoma (79); Obesity (79); neuroblastoma (76); gastric tumors (75); pneumonia (68); soft tissue sarcoma (66); bladder tumors (60); ovarian tumors (60); systemic lupus erythematosus (59); atherosclerosis (58); esophageal adenocarcinoma (57); serous ovarian cancer (51); chronic lymphocytic leukemia (50); classical Hodgkin lymphoma (49); biliary tract cancer (48); anemia (46); lung (45); neuroendocrine tumors (44); chordoma (42).
A further 1,065 diseases each share a sentence with CD274 in 39 papers or fewer.